SNORD138 (small nucleolar RNA, C/D box 138)
Synonyms: hsa-mir-3607; formerly MIR3607
Gene: MicroRNA gene on chromosome 5 (86,620,497 to 86,620,575, forward strand). Ensembl gene ENSG00000284078.
Gene Ontology:
Biological process: RNA processing
Cellular component: nucleolus